PRLHR (prolactin releasing hormone receptor)
Description:
Receptor for prolactin-releasing peptide (PrRP). Implicated in lactation, regulation of food intake and pain-signal processing.
Synonyms: PrRPR; GPR10; GR3
Tractability: Small molecule: a high-quality ligand is known; it belongs to a druggable protein family. Antibody: its Gene Ontology location is reachable by antibodies, with high confidence; UniProt places it where antibodies can reach, with medium confidence; UniProt predicts a signal peptide or a membrane-spanning region. PROTAC: a small molecule that binds it is known.
Target class: Prolactin-releasing peptide receptor; Peptide receptor (family A GPCR); Short peptide receptor (family A GPCR); Membrane receptor; Family A G protein-coupled receptor
Gene: Protein-coding gene on chromosome 10 (118,589,997 to 118,596,704, reverse strand). Ensembl gene ENSG00000119973.
Subcellular location: Cell membrane
Pathways (Reactome):
Signal Transduction: Peptide ligand-binding receptors
Gene Ontology:
Molecular function: protein binding; G protein-coupled receptor activity; neuropeptide receptor activity; neuropeptide Y receptor activity
Biological process: feeding behavior; female pregnancy; G protein-coupled receptor signaling pathway; neuropeptide signaling pathway
Cellular component: cilium; neuron projection; plasma membrane; membrane
Genetic constraint (gnomAD): Loss-of-function variants: 2 observed, 3.11 expected, observed/expected ratio (o/e) 0.64, 90% interval 0.26 to 1.71. That is too few expected variants to judge how well the gene tolerates losing a copy. Missense variants: 461 observed, 381.05 expected, observed/expected ratio (o/e) 1.21, 90% interval 1.12 to 1.31. Synonymous variants: 210 observed, 183.75 expected, observed/expected ratio (o/e) 1.14, 90% interval 1.02 to 1.28.
Homologues: Orthologues: chimpanzee PRLHR (99% identical), macaque PRLHR (98% identical), dog PRLHR (94% identical), rabbit PRLHR (93% identical), pig PRLHR (92% identical), guinea pig PRLHR (91% identical), mouse Prlhr (90% identical), rat Prlhr (89% identical), zebrafish PRLHR (42% identical). Paralogues in human: GPR83 (32% identical), NPY2R (32% identical), NPY4R (30% identical), NPY4R2 (30% identical), TACR1 (26% identical), NPY1R (25% identical), NPY5R (25% identical), TACR3 (25% identical), TACR2 (25% identical), PROKR2 (24% identical), MTNR1A (23% identical), PROKR1 (23% identical), and 21 more.
Diseases named in the same sentence as PRLHR in open-access papers:
PRLHR is named in the same sentence as 20 diseases in open-access papers, as found by Europe PMC text mining. Sharing a sentence is not in itself a finding about the gene and the disease. The quoted sentences say what the papers report.
Obesity (15 papers, 2014 to 2025). Accumulation of substantial excess body fat. "Given that children’s obesity outcomes have been linked to the genes PRLHR and TNXB, these genes need further study." (PMID 37239458, 2023). "PRLHR encodes a transmembrane protein for the prolactin-releasing hormone and has previously been associated with body weight control and obesity." (PMID 28814982, 2017). "In this study, we identified multiple rare variants in PRLHR (Prolactin Releasing Hormone Receptor), also known as GPR10, in cases with severe obesity and ancestry-matched controls, which we showed in cellular studies, impaired ligand binding and G protein-dependent signalling." (PMID 36922513, 2023). "It was also reported that PRLHR, as well as involvement in the physiological responses to central dministration of PrRP, may play roles in other processes, such as feeding behavior, pathogenesis of uterine fibroids, energy expenditure, obesity and the pivotal control of blood pressure." (PMID 26302849, 2015).
colorectal cancer (3 papers, 2015 to 2022). A primary or metastatic malignant neoplasm that affects the colon or rectum. "Our results provide evidence that variants of PRLHR gene are a protective factor in colorectal cancer and variants of HSPA12A gene are a protective factor in gastric cancer in the Chinese Han population." (PMID 26302849, 2015). "In this study, we showed that the PRLHR gene, which is mapped to chromosome 10q26.11, contained an SNP (genotype “A/T” of rs12413624) associated with a increased risk of colorectal cancer." (PMID 26302849, 2015). "We discovered the relationship between rs12413624 in the PRLHR gene and colorectal cancer in the allele and the log-additive models." (PMID 26302849, 2015). "The genotype “A/T” of rs12413624 in PRLHR gene was associated with a decreased risk of colorectal cancer in allele model analysis [odds ratio (OR) = 0.81; 95 % confidence interval (CI) = 0.68–0.97; p = 0.018] and log-additive model analysis (OR = 0.81; 95 % CI = 0.66–0.98; p = 0.032)." (PMID 26302849, 2015). "Additionally, PRLHR mutation is a protective factor in Chinese Han patients with colorectal cancer." (PMID 35800054, 2022). "We demonstrated a relationship between polymorphisms of PRLHR and HSPA12A gene and the risk of gastric and colorectal cancers in the Chinese Han population." (PMID 26302849, 2015). "This study shows that PRLHR gene is a protective factor in colorectal cancer and HSPA12A gene is a protective factor in gastric cancer." (PMID 26302849, 2015). "The aim of this study was to investigate the relationship between CHCHD3P1-HSP90AB7P, GRID1, HSPA12A, PRLHR, SBF2, POLD3, and C11orf93-C11orf92 genes and susceptibility to gastric and colorectal cancers in the Chinese Han population." (PMID 26302849, 2015). "The aim of this research was to study whether polymorphisms of CHCHD3P1-HSP90AB7P, GRID1, HSPA12A, PRLHR, SBF2, POLD3 and C11orf93-C11orf92 genes are associated with the risk of gastric and colorectal cancers in the Chinese Han population." (PMID 26302849, 2015).
Uterine leiomyoma (3 papers, 2023 to 2025). The presence of a leiomyoma of the uterus. "We reported previously that the loss of REST protein in uterine leiomyoma allows aberrant expression of GPR10 (PRLHR), a neuronal specific G-protein coupled receptor, leading to cell growth and survival via the PI3K/AKT-mTOR signal transduction pathway." (PMID 39314474, 2024).
Alzheimer disease (2 papers, 2022 to 2023). A progressive, neurodegenerative disease characterized by loss of function and death of nerve cells in several areas of the brain leading to loss of cognitive function such as memory and language. "Gene-based analyses implicated AGXT2 and CALN1 for VL, while analyses of protein-protein interactions implicated synaptic proteins previously associated with Alzheimer disease biology, SYT9 and NRXN1 for VSTM; ZFAND5, GRIK2, and ZC3H18 for VL; and PRLHR for paragraph recall." (PMID 35974141, 2022).
glioma (2 papers, 2021 to 2022). A benign or malignant brain and spinal cord tumor that arises from glial cells (astrocytes, oligodendrocytes, ependymal cells). "Taken together, these results show that PRLHR can be used as a marker to predict the prognosis of patients with glioma." (PMID 35800054, 2022). "The transcriptome data of 698 glioma tissues was downloaded from TCGA database and divided into two groups based on PRLHR expression." (PMID 35800054, 2022). "In this study, we aimed to explore the prognostic value of TMB and TMB-related PRLHR immune genes as prognostic markers in patients with gliomas." (PMID 35800054, 2022). "PRLHR expression in patients with low-grade gliomas is higher than that in patients with high-grade gliomas, including GBM, suggesting that the prognosis of high-grade gliomas is worse." (PMID 35800054, 2022). "Based on univariate and multivariate cox regression analysis, we identified five genes, FABP5, VEGFA, SAA1, ADM, and PRLHR, for prognosis prediction in patients with glioma." (PMID 35800054, 2022). "A series of genes such as EN1, S100A4, ANXA1, PDPN, IGFBP2 and CHI3L1 were upregulated in radiotherapy treated glioma patients, while other genes such as PRLHR, SFRP2, BRINP1, TRIM67, LHX5, KCNIP2 and NSG2 were downregulated." (PMID 34852024, 2021). "Additionally, a predictive model based on five HUB genes (FABP5, VEGFA, SAA1, ADM, and PRLHR) was constructed to predict OS in patients with gliomas." (PMID 35800054, 2022). "PRLHR can be used as a tumor inhibitory factor for the development of glioma, and has important guiding significance for the prognosis and immunotherapy of glioma." (PMID 35800054, 2022). "We used GO and KEGG enrichment analyses to predict the role of PRLHR in glioma." (PMID 35800054, 2022). "The results show that PRLHR may inhibit the occurrence and development of glioma by regulating immune cells and their ability to participate in the immune response." (PMID 35800054, 2022). "The clinical-related immune gene, PRLHR, can be used as an independent prognostic factor for patients with brain glioma, and it is negatively correlated with the grade of glioma and age of patients with glioma." (PMID 35800054, 2022). "Independent prognostic analysis showed that PRLHR could be used as an independent prognostic factor for patients with glioma, and clinical correlation analysis showed that it was significantly different from age and tumor grade." (PMID 35800054, 2022). "Moreover, PRLHR is related to the prognosis and survival rate of patients with glioma." (PMID 35800054, 2022). "Therefore, PRLHR may be a protective factor for the occurrence of gliomas and can be used as an independent prognostic marker for patients with gliomas." (PMID 35800054, 2022). "PRLHR is an immune gene related to TMB, and significantly differs from tumor grade and age of patients with glioma." (PMID 35800054, 2022). "Univariate and multivariate independent prognostic analysis showed that PRLHR and SAA1 were the independent predictor of glioma (univariate and multivariate analysis P < 0.05)." (PMID 35800054, 2022). "Therefore, PRLHR may be a suppressor of glioma tumorigenesis." (PMID 35800054, 2022). "Expression of PRLHR in patients with low-grade gliomas (WHO I-II) is higher than that in patients with high-grade gliomas (WHO III-IV), including GBM, suggesting that the prognosis of patients with high-grade gliomas is worse." (PMID 35800054, 2022). "Some studies have shown a negative correlation between the PRLHR expression levels and immune cells infiltration in LGG, but the role of PRHLR in glioma remains unclear." (PMID 35800054, 2022).
dementia (1 paper, 2023). Loss of intellectual abilities interfering with an individual's social and occupational functions. "We furthermore compared the PRLHR methylation in cfDNA with cognitive status and dementia scale." (PMID 38067107, 2023).
malnutrition (1 paper, 2024). Inadequate nutrition resulting from poor diet, malabsorption, or abnormal nutrient distribution. "Thus, the association between PRLHR and astrovirus diarrhea infections is not likely to be mediated by malnutrition." (PMID 38524222, 2024).
tumor (3 papers, 2021 to 2025). "We found that the higher the tumor grade and the older the age, the lower the PRLHR expression, which was verified by CGGA database and independent experimental data." (PMID 35800054, 2022).
PRLHR also shares sentences with these, for which no sentence is quoted: Anxiety (4 papers); depression (3); Insulin resistance (2); brain glioma (1); diabetes (1); gastric cancer (1); Hyperglycemia (1); Hyperinsulinemia (1); leiomyoma (1); neurodegenerative disease (1); pituitary adenoma (1); prediabetic (1).